ENSG00000275598 (zinc finger pseudogene)
Synonyms: LOC100533643
Gene: Processed pseudogene on chromosome 11 (63,469,376 to 63,470,944, forward strand). Ensembl gene ENSG00000275598.
Diseases named in the same sentence as ENSG00000275598 in open-access papers:
ENSG00000275598 is named in the same sentence as 1 disease in open-access papers, as found by Europe PMC text mining. Sharing a sentence is not in itself a finding about the gene and the disease.
ENSG00000275598 shares sentences with these, for which no sentence is quoted: myopia (1 paper).